AIF1 (allograft inflammatory factor 1)
Diseases named in the same sentence as AIF1 in open-access papers (continued):
Sharing a sentence is not in itself a finding about the gene and the disease.
sarcoidosis (1 paper, 2025). Sarcoidosis is a multisystemic disorder of unknown cause characterized by the formation of immune granulomas in involved organs. "The OR of sarcoidosis ranged from 0.02 (95% CI 0.00, 0.16) to 6.89 (95% CI 5.23,9.08) per SD increase in genetically predicted levels of protein CSNK2B and AIF1, respectively." (PMID 40075078, 2025).
tumor (324 papers, 2007 to 2026). "Except for M09, all other subtypes expressed macrophage markers such as CD68, C1QB, S100A9, and AIF1, suggesting that they are tumor-associated macrophages (TAMs)." (PMID 40260248, 2025). "Activated macrophages and microglial cells expressing AIF-1 have been reported to be linked to tumor malignancy and poorer prognosis." (PMID 40438577, 2025). "While Il4r and Igf1 mRNA was expressed in Cd68/Aif1-positive tumour-associated microglia throughout drug-treated PDOX, Il4 expression co-localised with Gfap/S100b-expressing astrocytes exclusive to the interface region of drug-treated PDOX." (PMID 37127652, 2023). "Allogeneic inflammatory factor-1 (AIF-1) overexpression has been reported to be associated with tumorigenesis and tumor metastasis." (PMID 36520870, 2022). "Third, we found that the AIF-1 expression is associated with tumor immunity." (PMID 37014322, 2023). "Furthermore, AIF-1 expression in NSCLC tissue was positively associated with aggressive tumor behavior as evidenced by lymph node metastasis, and advanced TNM stage." (PMID 36520870, 2022). "Furthermore, the link between AIF-1 expressions and specific studies, such as immune infiltration, immunological checkpoint genes (ICGs), tumor mutational burden (TMB), microsatellite instability (MSI), mismatch repair (MMR), and DNA methylation, was also thoroughly examined." (PMID 37014322, 2023). "Studies have identified mixed effects of AIF1 expression on tumour immune cell infiltration and prognosis." (PMID 41225774, 2025). "Cleaved/activated CASP3 immunoreactions occurred also in the tumor cell cytoplasm by covering similar but more moderate intensity ranges with a somewhat more frequent nuclear appearance, than of the AIF1 reactions." (PMID 40806359, 2025). "The AIF1 immunoreaction was cytoplasmic, often granular, suggesting mitochondrial localization in tumor cells with only very rare occurrence in cell nuclei, which would have indicated a direct induction of apoptosis." (PMID 40806359, 2025). "After filtering, the expression of SOX2 and AIF1 (which encodes the protein IBA1) aligned with the expected segmentation, confirming distinct transcriptional profiles between tumor cells and TAMs." (PMID 40960500, 2025). "In support of these findings, the KM Plotter for breast proteins analysis revealed massive survival benefits for patients with high AIF1 protein (UniProt ID: 095831) expression in all aspects of tumor prognostic estimates." (PMID 40806359, 2025). "To explore the impact of the AIF1 on the immune microenvironment, we employed the estimation algorithm to calculate the immunological scores, estimate scores, stromal scores, and tumor purity for each sample in the TCGA cohort." (PMID 38521928, 2024). "The findings indicated that low-expression AIF1 exhibited significantly lower immunological scores, estimate scores, stromal scores, and higher tumor purity." (PMID 38521928, 2024). "Our analysis revealed that AIF-1 exhibited a significant upregulation in 17 types of tumor tissues compared to their normal tissue counterparts." (PMID 37014322, 2023). "We confirmed Cd68/Aif1-expressing tumour-associated microglia and Gfap/S100b-expressing astrocytes in close proximity to proliferating (MKI67-positive) tumour cells within the interface of drug-treated PDOX." (PMID 37127652, 2023). "While the Tumor_2 had relative mild cancer hallmark signatures but expressed genes associated with tumor survival signal and drug resistance (IL32, TOX2, AIF1, AKAP12, CD38 etc.), and eventually became the main tumor subtype post-treatment." (PMID 36417130, 2023). "The data obtained from the study suggest a possible correlation between AIF-1 expression and immune activation in the tumor microenvironment (TME)." (PMID 37014322, 2023). "We discovered novel cell clusters in both tumor cells (HCC_HP) and neutrophils (Neu_AIF1) through our research." (PMID 37914817, 2023).
tumor (continued). "AIF-1 was mainly expressed in the cytoplasm of macrophages infiltrating the tumor tissue and positively correlated with IL-6 and VEGF expression in both clinical NSCLC samples and TCGA NSCLC samples." (PMID 36520870, 2022). "Another study shows that AIF1 is expressed by brain-infiltrating myeloid cells that enhance metastatic growth by promoting proliferation and reducing apoptosis of tumor cells (Zhanget al., 2015)." (PMID 33824914, 2021). "At the tumour margins, Aif1-positive cells showed a microglia-like morphology while they appeared more roundish in the tumour bulk (top vs. bottom row)." (PMID 33339831, 2020). "The expression of AIF1 was significantly correlated with the infiltration of lymphocytes in BC tissue, suggesting a role for AIF1 in the tumor microenvironment." (PMID 32796696, 2020). "RNA profiling of microenvironment-related genes revealed increased expression of markers for TAMs and resident microglia (Aif1, Itgam, Cd68 and Cx3cl1), and macrophage M1/M2 polarisation (Cd80 vs. Cd163) in knockdown tumours." (PMID 33339831, 2020). "We detected proteins DNMT1, ICAM1 and AIF1 as being highly expressed in the outlier presumed normal tissue compared to both other controls and tumor tissue from the same patients." (PMID 30419021, 2018). "AIF1 was overexpressed in the outlier samples as compared to both normal control samples (FC = 6.89x q = 0,053) and tumor samples (FC = 3.29x)." (PMID 30419021, 2018). "Effectively, a cumulative effect of inflammatory and tolerogenic immune responses in the tumor microenvironment controlled by AIF1 and PRRX1 are identified to dictate tumor growth and metastasis." (PMID 26272668, 2015). "AIF1 is also related to tumor microenvironment score, such as the high-expression AIF1 exhibited significantly higher immunological scores, estimate scores, stromal scores, and lower tumor purity." (PMID 38521928, 2024). "Moreover, AIF1 serves as a potential tumor marker involved in tumor immune cell infiltration and promoting tumor progression." (PMID 39254691, 2024). "This suggests that AIF-1 may play a role in modulating the immune response in tumor microenvironments." (PMID 37014322, 2023). "These discoveries offer novel insights into the potential involvement of AIF-1 in tumor immunity, which could aid in the identification of innovative therapeutic targets and predictive biomarkers for immunotherapy." (PMID 37014322, 2023). "As a result, epigenetic methylation of AIF-1 may impact the transcriptome of TCGA tumor cells, which could, in turn, influence the development and progression of tumors." (PMID 37014322, 2023). "We recently published a report showing that macrophages in the SHH medulloblastoma tumor microenvironment have anti-tumor properties, and that high expression of the macrophage marker AIF1 predicted better survival contrasting with the immune suppressive properties of macrophages in glioma." (PMID 37029430, 2023). "We analyzed genetic alterations of AIF-1 in tumor samples from the TCGA pan-cancer cohort." (PMID 37014322, 2023). "In addition, our research revealed a significant correlation between AIF-1 expression and the tumor microenvironment, tumor-infiltrating immune cells, immune subtypes, and biomarkers of immune checkpoint inhibitors." (PMID 37014322, 2023). "We then analyzed the associations between CXCL2 expression and classical macrophage phenotype markers of M0 (undifferentiated) (AIF1), M1 (anti-tumor) (IL12A, TNF, NOS2, PTGS2) and M2 (tumor-promoting) (IL10, CD163, TGFB1, CSF1R) in TCGA-LIHC cohort with Spearman’s rank correlation test." (PMID 36276119, 2022). "Further research is needed to establish whether AIF-1 might be useful as a biomarker of aggressive tumor behavior in patients with NSCLC." (PMID 36520870, 2022). "Additional research is merited to determine whether AIF-1 might be a useful biomarker of aggressive tumor behavior in patients with NSCLC." (PMID 36520870, 2022).
tumor (continued). "In this study, we demonstrated that AIF-1 protein expression was significantly upregulated in human NSCLC tissue compared with that in paired paracancer tissue, positively associated with tumor stage and metastasis, and negatively correlated with the outcomes of patients." (PMID 36520870, 2022). "Based on the known annotation of marker genes from the literature, we grouped cells of nine clusters into four cell types: GNP-like tumor cells (expressing Math1 and Grin2b), microglia (expressing Aif1 and Cd68), T cells (expressing Cd3d and Cd3e), and endothelial cells (expressing Cldn5 and Cdh5)." (PMID 34210306, 2021). "It is thus interesting to determine whether AIF1 expression in macrophages or microglia plays a functional role in these settings or serves as a marker that indicates cell reprogramming in the tumor microenvironment, as identified in our study." (PMID 33824914, 2021). "In addition, immunohistochemistry staining identified increased numbers of Aif1 (Iba1) positive cells in SOX10 KD compared to control tumours." (PMID 33339831, 2020). "In vitro study showed that AIF1 promoted tumor growth via the NF-κB/cyclin D1 pathway." (PMID 33186124, 2020). "The specific high content of AIF1 in the F4-T2 tumor versus F5-T1 may also be related to a higher immune cell infiltration." (PMID 29662647, 2018). "Our present findings support the hypothesis that AIF1 inhibition could be an indirect effect of reduced number of tumor infiltrating macrophages due to CR in CT-2A tumor." (PMID 21479220, 2011). "Whereas CXCL14 suppresses tumor growth, AIF1 seems to promote tumor cell proliferation." (PMID 21188144, 2010). "Therefore, it seems that the availability of AIF1 protein mainly in the mitochondria may both support caspase-independent apoptosis upon chemotherapy and reduce the tumor promoting dominance of oxidative phosphorylation." (PMID 40806359, 2025). "Therefore, we speculate that T-cell rejection is the main mechanism by which AIF-1 regulates immune cell tumor escape, tumor promotion, and metastasis." (PMID 37014322, 2023). "Moreover, AIF1 may promote this aggressive tumor function via the activation of p38-MAPK and JAK/STAT signaling." (PMID 37237507, 2023). "Hence, our results and those of others imply that AIF-1 might promote tumor progression by enhancing proliferation and migration." (PMID 36520870, 2022). "Thus, the pro-inflammatory effects of AIF-1 may contribute to the promotion of aggressive tumor behavior." (PMID 36520870, 2022). "In agreement with the RNA expression data, quantification of Aif1 staining showed an increase in tumour-associated macrophage infiltration in the SOX10 KD tumours (Aif1 positive area: NT: 4.57%; SOX10 KD: 17.11%; 10 fields of view in 3 tumours in each condition; P < 0.001)." (PMID 33339831, 2020). "Thus AIF1 within its hub may control expression of other TFs responsible for the development and function of immune cells involved in tumor growth." (PMID 26272668, 2015). "Our network analysis also identified key bridging roles for AIF1 and FGR, suggesting potential points of interaction between stromal and immune components of the tumor microenvironment." (PMID 41225774, 2025). "Colony-stimulating factor 1 (CSF1) secreted by HCC cells promotes overexpression of allograft inflammatory factor 1 (AIF1) in macrophages and induces a transformation of macrophages into the M2 phenotype, resulting in enhanced migration of tumor cells." (PMID 38957393, 2024). "Furthermore, AIF-1 may function as an oncogene and promote tumor progression in KIRC." (PMID 37014322, 2023). "In the present study, immunofluorescence staining of NSCLC samples showed that AIF-1 was mainly located in the cytoplasm of macrophages that infiltrated the cancerous tissue, and AIF-1 expression was higher in tumor tissue than in paracancer tissue." (PMID 36520870, 2022).
tumor (continued). "To achieve this objective, we investigated whether AIF-1 expression in tumor tissue samples from patients with NSCLC was associated with CD68 expression (a marker of monocytes such as macrophages), IL-6 expression, VEGF expression and clinicopathological features of aggressive tumor behavior." (PMID 36520870, 2022). "Furthermore, immunofluorescence double-labeling experiments demonstrated co-localization of AIF-1 and CD68 in cells within cancer nests, suggesting that AIF is mainly expressed in the cytoplasm of macrophages infiltrating the tumor tissue." (PMID 36520870, 2022). "In addition, both AIF1 isoforms, but mainly AIF1v1, were highly expressed in the less severe BC tumors (DCIS and luminal subtype) suggesting their involvement in tumor initiation and progression." (PMID 30386176, 2018). "Non-tumor components included endothelial cells (expressing VWF, CDH5, ECSCR, SLCO2A1, and MYCT1), pericytes (marked by RGS5, MCAM, and PDGFRB), normal oligodendrocytes (showing PTGDS, MBP, TF, and MOG expression), and TAMs (identified by CD14, AIF1, FCER1G, FCGR3A, TYROBP, and CSF1R)." (PMID 41394801, 2025). "The role and expression of AIF1 isoforms in the tumor microenvironment are also not known." (PMID 30386176, 2018). "This discovery implies that AIF1 is most probably not expressed in the epithelium and might rather be expressed via the tumor microenvironment (TME)." (PMID 30386176, 2018). "Moreover, the expression of AIF1 was upregulated in HCC tissue compared to adjacent healthy tissue, and correlated positively with the following clinicopathological characteristics: median tumor size, number of tumor deposits, Barcelona Clinic Liver Cancer stage and portal vein tumor thrombus." (PMID 37237507, 2023). "According to the TCGA dataset the microglia compartment based on AIF1 expression level did not parallel the TLRs upregulated expressions in mesenchymal subtype, suggesting that the tumor cells themselves may contribute to the increased expression of these receptors." (PMID 29912993, 2018). "The canonical markers EPCAM and KRT19 identified tumor cells, while CD3D, CD2, PTPRC, CD14, AIF1, CD79A, and COL1A2 validated non-tumor cells." (PMID 39955556, 2025). "Markers for total macrophages/microglia such as Adgre (F4/80) or Aif1 (IBA1) were not differentially expressed, suggesting that PTP4A2 expression did not affect macrophage accumulation inside the tumor." (PMID 38904264, 2024).
infection (164 papers, 2008 to 2026). The state of being infected such as from the introduction of a foreign agent such as serum, vaccine, antigenic substance or organism. "In particular, some proteins in Cluster A have a putative role in cellular mechanisms linked to host infection response, such as villin, gelsonin, and allograft inflammatory factor-1 (AIF-1)." (PMID 40443667, 2025). "This short infection period did demonstrate the anticipated macrophage control of the intracellular bacteria through up-regulation of complement, Aif1, Maf, and pathway enrichment of oxidative stress, phagosome formation, and HIF-1α signaling." (PMID 39813329, 2025). "Inthis regard, our data indicate a possible modifying effect ofhelminth infection on the expression of the Aif1 gene, but notits protein, in the hippocampus and cortex." (PMID 40144377, 2025). "This includes the upregulation of gene programmes involved in other neurodegenerative disorders, such as Apoe, Aif1, Cst7, Itgax, Tyrobp, and Trem2 at the point of infection in which clinical symptoms are detected." (PMID 36180478, 2022). "As follow-up experiments, relative amount of parasites and AIF1 expression within the splenic macrophages were assessed daily post-infection by flow cytometry." (PMID 33441583, 2021). "In these committed macrophages, in vitro infection with L. donovani resulted in marked depression of AIF1, as assessed by real time PCR." (PMID 33441583, 2021). "Ectopic overexpression of AIF1 in macrophages provided protection from infection, marked by robust pro-inflammatory cytokine production and efficient pathogen clearance." (PMID 33441583, 2021). "donovani in vivo or in vitro infection using BMDM approaches had a correlative reduction in frequency of AIF1+ macrophages." (PMID 33441583, 2021). "After DGE analysis, we assessed the transcriptional and translational levels of AIF1, which revealed upregulation of AIF1 transcripts and protein in PAMs in response to infection with CSFV Shimen." (PMID 32110485, 2020). "In the present study, AIF1 was identified as a key player contributing to CSFV Shimen infection in porcine alveolar macrophage (PAM) 3D4/21 cell line." (PMID 32110485, 2020). "Here, we describe a study that showed upregulated AIF1 expression in porcine alveolar macrophage (PAM) 3D4/21 cell line during CSFV Shimen infection using digital gene expression (DGE) tag profiling and molecular biological methods." (PMID 32110485, 2020). "This preliminary work demonstrates for the first time the possible role of AIF1 in front of a CSFV Shimen infection, and more information will be expound in future studies." (PMID 32110485, 2020). "However, in response to the infection, overfed rats expressed less Aif1 in their HC, and the microglial cells in their DG presented a more branched phenotype compared to the normal-fed infected rats." (PMID 39469711, 2024). "Arrdc1 is involved in a variety of processes including cellular protein metabolism, extracellular vesicle biogenesis, and negative regulation of the Notch signaling pathway.The down-regulated differential protein AIF1 has been identified as an up-regulated protein of infection." (PMID 36341346, 2022). "As in vivo experiments showed a correlation of L. donovani infection with reduced AIF1 expression, studies next assessed whether infection directly antagonized AIF1 using in vitromodels." (PMID 33441583, 2021). "Many cytokines of host maybe affect CSFV replication, and we considered AIF1-mediated microenvironment in PAM 3D4/21 cells contributed to CSFV Shimen infection." (PMID 32110485, 2020). "Thus, we select IL6 as an inflammatory indicator to clarify the role of AIF1 on CSFV Shimen infection in PAMs 3D4/21 cells." (PMID 32110485, 2020). "Although Aif1−/− recipient mice, which possessed Aif1-deficient M cells and wild-type haematopoietic cells, had comparable levels of total IgA in their faeces after infection as before infection, no induction of anti-Y." (PMID 28224999, 2017).